NSUN4 (NOP2/Sun RNA methyltransferase 4)
Description:
Mitochondrial RNA cytosine C(5)-methyltransferase that methylates cytosine to 5-methylcytosine (m5C) in various RNAs, such as rRNAs, mRNAs and some long non-coding RNAs (lncRNAs). Involved in mitochondrial ribosome small subunit (SSU) maturation by catalyzing methylation of mitochondrial 12S rRNA; the function is independent of MTERFD2/MTERF4 and assembled mitochondrial ribosome large subunit (LSU). Targeted to LSU by MTERFD2/MTERF4 and probably is involved in a final step in ribosome biogenesis to ensure that SSU and LSU are assembled. In vitro can methylate 16S rRNA of the LSU; the methylation is enhanced by MTERFD/MTERF4. Also acts as a regulator of innate immunity by marking double-stranded mitochondrial RNAs(mt-dsRNAs) generated in response to stress: catalyzes m5C modification on mitochondrial RNAs, such as a mRNAs and lncRNAs, with a preference for the termini of light-strand lncRNAs, promoting their degradation and cytosolic release. Modified light-strand lncRNAs are then recognized by C1QBP reader and recruited to the mitochondrial degradosome complex, which promotes their degradation.
Synonyms: MGC22960; SHTAP
Tractability: Small molecule: a structure with a bound ligand is known. PROTAC: ubiquitination databases record sites on it; its protein half-life has been measured.
Gene: Protein-coding gene on chromosome 1 (46,340,719 to 46,369,218, forward strand). Ensembl gene ENSG00000117481.
Subcellular location: Mitochondrion
Pathways (Reactome):
Metabolism of RNA: rRNA modification in the mitochondrion
Gene Ontology:
Molecular function: mitochondrial ribosomal large subunit rRNA binding; mRNA (cytidine-5-)-methyltransferase activity; protein binding; RNA methyltransferase activity; rRNA (cytosine-C5-)-methyltransferase activity; rRNA methyltransferase activity; methyltransferase activity; S-adenosylmethionine-dependent methyltransferase activity
Biological process: mitochondrial large ribosomal subunit assembly; mitochondrial RNA catabolic process; mitochondrial RNA modification; rRNA methylation; rRNA processing; RNA processing
Cellular component: mitochondrial matrix; mitochondrion
Genetic constraint (gnomAD): Loss-of-function variants: 31 observed, 45.05 expected, observed/expected ratio (o/e) 0.69, 90% interval 0.52 to 0.93. The upper end of that interval is the gene's LOEUF score, 0.93, which puts it in group 3 of 6, group 1 being the genes least tolerant of losing a copy. Missense variants: 439 observed, 499.33 expected, observed/expected ratio (o/e) 0.88, 90% interval 0.81 to 0.95. Synonymous variants: 167 observed, 193.75 expected, observed/expected ratio (o/e) 0.86, 90% interval 0.76 to 0.98.
Homologues: Orthologues: chimpanzee NSUN4 (99% identical), guinea pig NSUN4 (85% identical), pig NSUN4 (84% identical), rat Nsun4 (83% identical), rabbit NSUN4 (83% identical), tropical clawed frog nsun4 (61% identical), zebrafish nsun4 (56% identical), Drosophila melanogaster l(2)10685 (39% identical), Caenorhabditis elegans nsun-4 (36% identical). Paralogues in human: NSUN3 (30% identical), NSUN2 (22% identical).
Diseases named in the same sentence as NSUN4 in open-access papers:
NSUN4 is named in the same sentence as 40 diseases in open-access papers, as found by Europe PMC text mining. Sharing a sentence is not in itself a finding about the gene and the disease. The quoted sentences say what the papers report.
glioma (9 papers, 2020 to 2025). A benign or malignant brain and spinal cord tumor that arises from glial cells (astrocytes, oligodendrocytes, ependymal cells). "While NSUN2 and NSUN4 are highly expressed in glioma, single-cell bioinformatic analysis has revealed that malignant cells present the lowest NSUN5 expression levels among the different cell types that make up the tumour mass." (PMID 40860147, 2025). "NSUN4 is highly expressed in glioma tissues and cells, and high m5C levels are negatively correlated with the prognosis of patients with glioma." (PMID 41462962, 2025). "In the glioma mechanism, NSUN4-mediated m5C changes regulate ALYREF binding to CDC42 mRNA, affecting CDC42 mRNA stability." (PMID 41462962, 2025). "We observed the high expression levels of METLL8, METLL2A, TRMT112, METTL2B, GTPBP3, METTL6, and NSUN4 in cells in the S, G2M, and G1 phases, which were similar for astrocytes, glioma cells, and oligodendrocytes." (PMID 38824202, 2024). "Through survival analysis, this study constructed a low‐grade glioma prognostic model with 4 genes (NSUN4, NSUN7, DNMT1 and NSUN6) and drew a nomogram accordingly." (PMID 33400376, 2021). "We obtained six genes associated with prognosis (P < 0.01), among which NOP2, NSUN2, NSUN4, NSUN5, and NSUN7 acted as risk factors (HR > 1), and NSUN6 played a protective role (HR < 1) in gliomas." (PMID 32974125, 2020). "According to a recent study on gliomas, five genes related to m5C methyltransferase were identified to construct a risk signature (5MM) and were used to predict glioma prognosis, including NOP2, NSUN4, NSUN5, NSUN6 and NSUN7." (PMID 36637205, 2023). "Furthermore, as shown in the figure, we found that the protein expression of NOP2 and NSUN4 in high-grade glioma tissues were much higher than those in low-grade glioma tissues." (PMID 32974125, 2020). "Furthermore, NSUN4 enhances m5C modification of mRNA, promoting glioma malignant progression." (PMID 41462962, 2025). "NSUN4-mediated high m5C levels promoted ALYREF binding to CDC42 mRNA and regulated its stability, thereby promoting glioma malignant progression." (PMID 41462962, 2025). "In glioma cells, it was observed that the expression of genes related to MRM, like GTPBP3, METTL2A, METTL6, METTL8, NSUN4, and TRMT61A, showed positive correlation with the expression of HAVCR2, PVR, TNFRSF25 and TNFSF15 as revealed by scRNA-seq analysis." (PMID 38824202, 2024). "The expression of HAVCR2, PVR, TNFRSF25, and TNFSF15 showed a positive correlation with the expression of numerous MRM-related genes like GTPBP3, METTL2A, METTL6, METTL8, NSUN4, and TRMT61A in glioma cells." (PMID 38824202, 2024). "Applying univariant and multivariant CoxPH analysis, we proved that ALYREF, DNMT3B, NSUN4 and NSUN6 were independent prognostic factors for glioma." (PMID 37934565, 2023). "Our findings revealed that MRM2, NSUN4, TFB1M, and TRMT2B were correlated significantly with most immunomodulators in glioma, whereas MRM1 and RPUSD4 were correlated negatively." (PMID 34566979, 2021). "All five RNA:m5C methyltransferase genes, NOP2, NSUN4, NSUN5, NSUN6, and NSUN7, were differentially expressed between normal brain tissues, low grade and high grade glioma tissues." (PMID 32974125, 2020). "The expression of NOP2, NSUN2, NSUN4, NSUN5, and NSUN7 were positively correlated in gliomas." (PMID 32974125, 2020). "Moreover, we observed protein expression of MRM1, MRM3, TRMT2B, and NSUN4 to be significantly different between low- and high-grade gliomas, whereas other regulators could not be obtained due to lack of data." (PMID 34566979, 2021). "The results showed that NSUN4, NSUN7, DNMT1, DNMT3B, DNMT3A, NOP2 and NSUN5 were negatively correlated with the overall survival of low‐grade glioma, while NSUN6 was positively correlated with the overall survival." (PMID 33400376, 2021).
hepatocellular carcinoma (9 papers, 2021 to 2025). A malignant tumor that arises from hepatocytes. "Microtubule-associated serine-threonine (MAST) kinase is associated with gene rearrangement in breast cancer and related pre-invasive lesions, while Gene Set Enrichment Analysis (GSEA) indicated that NSUN4 was associated with methylation and demethylation processes in hepatocellular carcinoma." (PMID 36609218, 2023). "The m5C methylation affects the survival risk associated with many tumors, and in hepatocellular carcinoma, high expression of NSUN4 was significantly associated with survival outcomes, NSUN4 was also associated with increased risk of breast, ovarian, and prostate cancers." (PMID 37183262, 2023). "NOP2/Sun RNA methyltransferase 4 (NSUN4) is a prognostic indicator for hepatocellular carcinoma (HCC)." (PMID 39634439, 2024). "NSUN4—A study found that m5C-related genes play an essential role in tumor progression in hepatocellular carcinoma and that high expression of NSUN4 correlated with survival outcome in this type of cancer." (PMID 33917098, 2021). "NSUN4 promotes the malignant progression of hepatocellular carcinoma." (PMID 36698387, 2022). "In addition, NSUN4 is upregulated in hepatocellular cancer and shows excellent performance as a biomarker for the prognosis of hepatocellular carcinoma." (PMID 36246622, 2022). "NSUN4 is aberrantly expressed in lung adenocarcinoma, hepatocellular carcinoma, and clear cell renal cell carcinoma and may be utilized to predict prognosis." (PMID 35562754, 2022).
prostate carcinoma (6 papers, 2017 to 2025). A carcinoma that arises from epithelial cells of the prostate gland. "This further suggests that the causal relationship between NSUN4 and breast and prostate cancer identified in this study is robust." (PMID 36634566, 2023). "For prostate cancer, one SD increase of NSUN4 expression was associated with 6% higher risk of cancer (OR: 1.06, 95% CI: 1.03–1.09, PSMR = 1.01 × 10−5)." (PMID 36634566, 2023). "Most importantly, our results show that the expression level of NSUN4 increased by rs41293273 is associated with higher risk of both breast cancer and prostate cancer." (PMID 36634566, 2023). "In addition, we identified a shared putative causal gene, NSUN4, for both breast and prostate cancer." (PMID 36634566, 2023). "Importantly, we identified additional 1 genetic locus related to NSUN4 expression and 2 loci related to NSUN4 methylation that were causally associated with both breast and prostate cancer." (PMID 36634566, 2023). "In breast, ovarian, and prostate cancers, NSUN4 operates as a cancer risk locus." (PMID 35211172, 2022). "NSUN4 acts as cancer risk loci (Breast, Ovarian, and Prostate Cancer), and the identified MTERF4-NSUN4 axis plays a unique role in the biogenesis of mitochondrial ribosomes." (PMID 32974125, 2020). "NSUN3 and NSUN4 have received less attention in prostate cancer research, but they may play a role in chemotherapy resistance and tumor advancement, potentially serving as risk factors for prostate cancer." (PMID 40809690, 2025). "Furthermore, our phenome-wide scan analysis showed that the causal relationship between NSUN4 and both breast and prostate cancers was not caused by horizontal pleiotropy." (PMID 36634566, 2023). "Three fusion transcripts, TMEM219-TAOK2, NSUN4-FAAH, and ACER3-B3GNT6, show a functional implication to prostate cancer development and progression." (PMID 28467780, 2017).
cardiomyopathy (5 papers, 2014 to 2025). A disease of the heart muscle or myocardium proper. "The pathological significance of GTPBP7, MTERF4, and NSUN4 is demonstrated by their association with cardiomyopathy, which is a common feature of mitochondrial diseases." (PMID 34609277, 2021). "Here, we show that inactivation of the Nsun4 gene, encoding a mitochondrial m5C-methyltransferase, causes embryonic lethality, whereas tissue-specific disruption of Nsun4 in the heart causes cardiomyopathy with mitochondrial dysfunction." (PMID 24516400, 2014). "NSUN4 deficiency also related to mitochondrial dysfunction and caused cardiomyopathy." (PMID 40405297, 2025). "However, abolition of NSUN4 is embryonically lethal and a conditional NSUN4 knockout in mouse heart tissue was found to cause cardiomyopathy." (PMID 30704115, 2019). "NSUN4 is essential for embryonic development in mice and tissue-specific conditional knockout of NSUN4 showed that in heart, lack of NSUN4 leads to progressive cardiomyopathy." (PMID 28752201, 2018).
breast carcinoma (3 papers, 2022 to 2023). "Analysis on breast cancer molecular subtypes with NSUN4 methylation showed a similar causal association but only for luminal A-like breast cancer." (PMID 36634566, 2023). "However, our results showed that rs5013329 related to NSUN4 methylation was associated with decreased risk of breast cancer only." (PMID 36634566, 2023). "For breast cancer, one SD decrease of FDPS expression was associated with 34% lower risk (OR: 0.66, 95% CI: 0.49–0.83, PSMR = 9.77 × 10−7) while 1 SD increase of NSUN4 expression was associated with 5% higher risk (OR: 1.05, 95% CI: 1.03–1.07, PSMR = 5.24 × 10−6)." (PMID 36634566, 2023). "The increased expression of NSUN4 and SERAC1 has been described in breast cancer." (PMID 36466711, 2022).
liver cancer (3 papers, 2021 to 2025). An epithelial or non-epithelial malignant neoplasm that arises from the liver. "The m5C methyltransferase NSUN4 recognizes protein ALYREF associated with liver cancer outcomes." (PMID 35686101, 2022). "Additionally, NSUN4 exacerbates liver cancer and may serve as a new prognostic marker for liver cancer." (PMID 41256854, 2025).
lung carcinoma (3 papers, 2023 to 2025). "NSUN4 is highly expressed in lung cancer tissues, consistent with the trend of circERI3 expression in lung cancer." (PMID 41462962, 2025). "The NSUN4 expression level correlated positively with the diameter of lung cancer, and the NSUN4-high expression group had a shortened OS." (PMID 41462962, 2025). "m5C microarray analysis determined that circERI3 contains the m5C modification, and NSUN4-mediated m5C modification of circERI3 increased its nuclear output, promoting lung cancer progression." (PMID 41462962, 2025).
lung squamous cell carcinoma (3 papers, 2023 to 2025). "Related studies have also confirmed that NSUN3 and NSUN4 can predict the prognosis of lung squamous cell carcinoma and regulate the immune microenvironment." (PMID 40370440, 2025). "NSUN3 and NSUN4 have also been found to be related to immune cells in lung squamous cell carcinoma (LUSC); notably, NSUN3 was closely associated with CD8+ T cell infiltration, and NSUN4 was closely associated with neutrophils." (PMID 37485079, 2023). "In lung squamous cell carcinoma (LUSC), the m5C regulatory factors NSUN3 and NSUN4 are highly expressed compared to normal lung tissue and are associated with poor prognosis." (PMID 40370440, 2025).
systemic lupus erythematosus (3 papers, 2025 to 2026). An autoimmune multi-organ disease typically associated with vasculopathy and autoantibody production. "In parallel, NSUN4-mediated m5C modification promotes CD8+ T cell exhaustion in systemic lupus erythematosus (SLE) by elevating CD74 expression and activating CD44-mTOR-dependent mitophagy." (PMID 41424859, 2026). "The therapeutic effect of LPH‐nanoparticle delivered Nsun4–siRNA was confirmed in spontaneous lupus mice and pristane‐induced SLE mice in vivo." (PMID 40761479, 2025). "Spontaneous lupus MRL/lpr mice were used to investigate the role of Nsun4 in SLE progression, with normal C57L/6 mice as a control." (PMID 40761479, 2025). "NSUN4 knockdown reduces CD74 expression, suppresses exhaustion, and alleviates autoimmune responses and renal damage, indicating that NSUN4-mediated m5C modifications of mitophagy are critical for CD8+ T cell dysfunction in systemic lupus erythematosus pathogenesis." (PMID 41194917, 2025).
clear cell renal cell carcinoma (2 papers, 2022 to 2024). "Li et al8 discovered a similar result in clear cell renal cell carcinoma, indicating that NSUN4 serves as a marker for diagnosis and prognosis." (PMID 39634439, 2024). "In clear cell renal cell carcinoma (ccRCC), the mRNA levels of NOP2 and NSUN4 are higher in tumor tissues than in normal tissues, whereas the mRNA levels of NSUN6 and m5C eraser TET2 are lower." (PMID 35562754, 2022).
head and neck squamous cell carcinoma (2 papers, 2021). A squamous cell carcinoma that arises from any of the following anatomic sites: lip and oral cavity, nasal cavity, paranasal sinuses, pharynx, larynx, and salivary glands. "NSUN4, NSUN5, NSUN6 and NSUN7 are associated with cancer development in HCC, head and neck squamous cell carcinoma (HNSCC), pancreatic cancer and glioma 29, 114-116." (PMID 34512153, 2021).
renal cell carcinoma (2 papers, 2023 to 2025). "NOP2, NSUN2, and NSUN5 mRNA were significantly upregulated in renal cell carcinoma cell lines (786-O, Caki-1) compared to a human tubular epithelial immortalized cell line (HK-2), while NSUN4 was downregulated in the renal carcinoma cell lines." (PMID 41462962, 2025). "Furthermore, NOP2, NSUN2, and NSUN5 mRNA were significantly upregulated in renal cell carcinoma tissue, while NSUN4 mRNA was downregulated." (PMID 41462962, 2025). "NSUN4 and NSUN6 as model genes participate in the prognostic model of renal cell carcinoma." (PMID 37934565, 2023).
acute lymphoblastic leukemia (1 paper, 2025). Leukemia with an acute onset, characterized by the presence of lymphoblasts in the bone marrow and the peripheral blood. "The NOP2 rs3764909 and NSUN4 rs10252 variants enhanced the risk of acute lymphoblastic leukemia in children and are considered potential biomarkers of pediatric acute lymphoblastic leukemia." (PMID 41462962, 2025).
leukemia (1 paper, 2022). A malignant (clonal) hematologic disorder, involving hematopoietic stem cells and characterized by the presence of primitive or atypical myeloid or lymphoid cells in the bone marrow and the blood. "The MRD in the marrow of pediatric ALL samples with different NOL1 rs3764909 and NSUN4 rs10252 alleles after treatment with Chinese Children Cancer Group chemotherapeutics (CCCGs) or South China Children Leukemia Group chemotherapeutics (SCCLGs) was detected." (PMID 36698387, 2022).
neuroblastoma (1 paper, 2025). Neuroblastoma (NB) is the most common solid, extracranial childhood tumor. "A survey of 402 patients with neuroblastoma and 473 controls, followed by TaqMan analysis, revealed that NSUN4 rs10736428 polymorphism and increased susceptibility to neuroblastoma were closely associated." (PMID 41462962, 2025).
Obesity (1 paper, 2025). Accumulation of substantial excess body fat. "This may suggest a potential link between NSUN4 expression and the increase of immune cells in obesity." (PMID 41030849, 2025).
primary open-angle glaucoma (1 paper, 2026). "Clinically, NSUN4 levels were significantly reduced in the aqueous humor of patients with primary open-angle glaucoma compared to controls." (PMID 41984922, 2026). "Together, these findings establish NSUN4 as an m5C-dependent activator of the SHH pathway that protects retinal cells against excitotoxic injury, nominating it as a novel candidate for glaucoma neuroprotection." (PMID 41984922, 2026).
rectal cancer (1 paper, 2023). A primary or metastatic malignant neoplasm that affects the rectum. "Therefore, to further substantiate the results of the bioinformatics analysis, TMAs from patients with rectal cancer were immunohistochemically stained for NSUN4, NSUN7, and DNMT1." (PMID 36911744, 2023).
thyroid cancer (1 paper, 2023). "We found five TAD blocks with CoMut genes/events specific to ATC with certain mutation frequency in The Cancer Genome Atlas Thyroid Cancer (TCGA-THCA) cohort, including CoMut pairs MAST/NSUN4, AM129B/TRUB2, COL5A1/PPP1R26, PPP1R26/GPSM1/CCDC183, and PRAC2/DLX4." (PMID 36609218, 2023).